NLRP3 (NLR family pyrin domain containing 3)
Diseases named in the same sentence as NLRP3 in open-access papers (continued):
Sharing a sentence is not in itself a finding about the gene and the disease.
multiple sclerosis (continued). "The dysregulation of NLRP3 inflammasome has been shown to be related with a variety of diseases, including multiple sclerosis, diabetes, atherosclerosis, Alzheimer’s disease, inflammatory bowel disease, and many other autoimmune diseases." (PMID 33785039, 2021). "Type I IFN therapy is ineffective for all varieties of multiple sclerosis, and the NLRP3 inflammasome seems to be the primary determining factor." (PMID 34443594, 2021). "Since then, single nucleotide polymorphisms (SNPs) in NLRP1, NLRP3 and NLRC4 have been associated with many autoimmune diseases including IBD, celiac disease, multiple sclerosis and autoimmune diabetes." (PMID 34177937, 2021). "Neurological manifestations and the co-occurrence of multiple sclerosis (MS) have been reported in patients with autoinflammatory diseases (AID) and variants of the NLRP3-, MEFV-, or TNFRSF1A gene." (PMID 32563262, 2020). "NLRC4 and NLRP3 inflammasome activation, as important actors, are involved in lysophosphatidylcholine-induced astrogliosis and microgliosis of multiple sclerosis." (PMID 33551822, 2020). "The NLRP3 inflammasome has been reported to be involved in the development of multiple sclerosis through the secretion of IL-1β and IL-18." (PMID 30233319, 2018). "So far, several agents targeting on the inhibition of the NLRP3 inflammasome have been demonstrated to be effective in the treatment of multiple sclerosis or shown on the mice models of multiple sclerosis (experimental autoimmune encephalomyelitis, EAE)." (PMID 30233319, 2018). "As a result, pharmacological inhibition of the NLRP3 inflammasome has been regarded as a potential target for the treatment of multiple sclerosis." (PMID 30233319, 2018). "The NLRP3 inflammasome signaling pathway is involved in various neuroinflammatory diseases, including multiple sclerosis and the EAE and cuprizone models." (PMID 28732510, 2017). "Previous studies have demonstrated that the NLRP3 inflammasome plays an essential role in neuroinflammatory diseases including multiple sclerosis." (PMID 28732510, 2017). "Possible involvement of the NLRP3 inflammasome (or inflammasomes) in the development of multiple sclerosis (MS) was suggested in a number of studies." (PMID 23365725, 2013). "Both NLRP1 and NLRP3 exhibited increased expression in RE brain specimens relative to controls with mesial temporal sclerosis and multiple sclerosis." (PMID 24330827, 2013). "In multiple sclerosis (MS), NLRP3 knockout mice model of disease shows reduced demyelination, while another study shows NLRP3 involvement in migration of T-helper cells into CNS." (PMID 23843682, 2013). "CD4+CD45RO+ memory T-cells from multiple sclerosis (MS) patients showed a reduced ability to suppress NLRP3 inflammasome activation, however their suppressive ability was recovered following in vivo treatment with IFNβ." (PMID 22768094, 2012). "Cardiac fibrosis and multiple sclerosis severity can be limited by NLRP3 inflammasome inhibitor." (PMID 35379787, 2022). "Interestingly, a small-molecule inhibitor of NLRP3 was recently shown to attenuate the severity of experimental autoimmune encephalomyelitis, a disease model of multiple sclerosis." (PMID 32411143, 2020). "Activation of the NOD-like receptor protein 3 (NLRP3) inflammasome is involved in the maturation and secretion of IL-1β and IL-18 and, thus, plays a key role in the pathogenesis of many inflammatory conditions, including multiple sclerosis (MS)." (PMID 31736980, 2019). "NLRP3 was activated in multiple sclerosis and induced the secretion of IL-1β as well as IL-18." (PMID 31892810, 2019). "However, there were also studies demonstrating the limitation of the application of interferon-β in the treatment of the multiple sclerosis or EAE, showing that interferon-β therapy was effective against multiple sclerosis or EAE only in the NLRP3 inflammasome-dependent EAE." (PMID 30233319, 2018).
multiple sclerosis (continued). "LPS stimulation upregulates the expression of the inflammasome related genes, NLRP3, Caspase-1, and IL-1β in PBMC from multiple sclerosis compared to healthy controls." (PMID 27795729, 2016). "Gli is a hypoglycemic agent that can inhibit NLRP3 mediated production of IL-1β by blocking P2X7 ion-channels; this compound also modulates TRPM4, a cation channel that mediates axonal and neuronal degeneration in Multiple Sclerosis (MS)." (PMID 38139851, 2023). "DMF, an approved treatment of multiple sclerosis, as well as DMI, 4OI and MMF, inhibited NLRP3 activation in macrophages in response to lysophosphatidylcholine, which is used to induce demyelination, suggesting a possible mechanism for DMF in multiple sclerosis through NLRP3 inhibition." (PMID 35137954, 2022). "For example, by targeting directly to the NATCH domain of NLRP3, MCC950 has been shown to effectively block NLRP3 inflammasome assembly and attenuate the severity of experimental autoimmune encephalomyelitis in a mouse model of multiple sclerosis." (PMID 33679781, 2021). "Stratification by disease type showed a significant association of the NLRP3 rs10754558 G allele with type 1 diabetes (T1D), RA, and systemic lupus erythematosus (SLE), but not with celiac disease (CD), multiple sclerosis (MS), or myasthenia gravis (MG)." (PMID 34367252, 2021). "Contrary to the protective role of CB2R in diabetic inflammation, in a mouse model of experimental autoimmune encephalomyelitis (EAE) (an experimental model for human multiple sclerosis), CB2R mRNA and NLRP3 protein expressions were significantly higher with unchanged CB1R mRNA expression." (PMID 33584697, 2020). "Inflammasome-driven inflammation is postulated to play a role in multiple sclerosis (MS), but there is no direct evidence that the nod-like receptor protein 3 (NLRP3) inflammasome is involved in MS pathogenesis." (PMID 29780394, 2018). "For example, the NLR family, pyrin domain containing 3 (NLRP3) inflammasome, which is known to sense a wide variety of pathogens, can also change the course of experimental autoimmune encephalomyelitis (EAE), an animal model of multiple sclerosis (MS)." (PMID 28796840, 2017). "Activated IFNβ–primed CD4+CD45RO+ memory T-cells from multiple sclerosis (MS) patients were not as effective in suppressing NLRP3 inflammasome activation as compared to healthy controls." (PMID 22768094, 2012). "Moreover, there is evidence that astrocytes can express all the components of the NLRP3 inflammasome (NLRP3, ASC and caspase-1), and produce IL-1β in various central nervous system diseases, such as multiple sclerosis, neuromyelitis optica, and cerebral infarction." (PMID 37921870, 2023). "Itaconate and fumarate derivatives also inhibited NLRP3 activation induced by lysophosphatidylcholine (LPC), a lipid molecule used to induce demyelination in models of multiple sclerosis, further highlighting a potential mechanism of DMF action in multiple sclerosis treatment." (PMID 35137954, 2022). "Pharmacological inhibition of NLRP3 inflammasome activation and IL-1β production with specific antagonists, such as MCC950, has exhibited plausible effects on preventing neurological impairment of multiple sclerosis, neurodegenerative diseases, and traumatic brain injury." (PMID 33676524, 2021). "More recently, a newly developed, potent, and selective inhibitor of NLRP3, MCC950, significantly inhibited IL-1β production in an animal model of multiple sclerosis, which could be a potential therapeutic agent for other NLRP3-associated neuroinflammatory conditions." (PMID 28127491, 2017). "Type I IFN treatment is not effective for all types of multiple sclerosis, and the NLRP3 inflammasome may be a key determinant." (PMID 26594174, 2015).
multiple sclerosis (continued). "The innate immune system plays an important role in multiple sclerosis and infections have been shown to trigger MS exacerbations, thus the regulation of TLR and ATP-induced NLRP3 inflammasome activation by IFNβ might contribute to the beneficial effects of IFNβ treatment in MS." (PMID 22768094, 2012). "Multiple sclerosis is a neurodegenerative disease characterized by chronic inflammation; inflammasome-driven inflammation is postulated to play a role in MS, but as of today, there is no direct evidence that the NLRP3 inflammasome is involved in MS pathogenesis." (PMID 29780394, 2018). "Given the importance of NLRP3 inflammasome in the pathogenesis of many inflammatory diseases such as peritonitis, multiple sclerosis and obesity, understanding the positive and negative regulation of NLRP3 inflammasome may provide insight into pathology and identify new therapeutic strategies." (PMID 29255148, 2017). "A small-molecule inhibitor (MCC950), specifically targeting NLRP3 inflammasome activation (ASC oligomerization) but not AIM2, NLRC4 or NLRP1 inflammasomes, was able to attenuate mouse models of multiple sclerosis and Parkinson’s disease." (PMID 34177937, 2021).
myocardial ischemia (105 papers, 2016 to 2026). A disorder of cardiac function caused by insufficient blood flow to the muscle tissue of the heart. "NLRP3 inflammasome brings about the sterile inflammatory reaction provoked by tissue injury and influences the causative pathology of myocardial ischemia–reperfusion injury." (PMID 34443594, 2021). "Therefore, it is important to find safe and effective NLRP3 inflammasome inhibitors from Chinese Medicine, to improve myocardial ischemia resistance and reduce the loss of myocardial cells." (PMID 35615687, 2022). "In patients with MI, concentrations of NLRP3 inflammasome and associated inflammatory factors are markedly elevated in peripheral blood samples, particularly following myocardial ischemia-reperfusion injury, indicating that NLRP3 may serve as a prognostic indicator." (PMID 41194915, 2025). "An example search string was: (“myocardial ischemia reperfusion injury” OR “MIRI”) AND (pyroptosis OR inflammasome OR NLRP3 OR GSDMD) AND (therapy OR treatment OR intervention)." (PMID 41487823, 2025). "UA aggravates myocardial ischemia reperfusion-induced activation of the NLRP3 inflammatory cascade and pyroptosis by promoting ROS generation, and leads to DNA damage and apoptosis of myocardial cells." (PMID 40710003, 2025). "Activation of the NLRP3 inflammasome plays a crucial role in promoting myocardial ischemia/reperfusion (MI/R) injury." (PMID 39925805, 2025). "Overexpressing FTO in osteoarthritis models improves cartilage integrity and diminishes inflammation by modulating TLR4/MyD88/NF-κB signaling and NLRP3 inflammasome activity, which are relevant in myocardial ischemia/reperfusion injury." (PMID 39980685, 2025). "It has recently been shown that neutrophil cells themselves also release NLRP3 in the early inflammatory phase of myocardial ischemia, and that NLRP3 is not only a precursor but also a stimulus for NETosis." (PMID 40508157, 2025). "Since 2014, Professor Abbate has consistently explored the therapeutic potential of inhibiting inflammasome activity via NLRP3 to reduce infarct size following myocardial ischemia/reperfusion (I/R) in mice." (PMID 40018377, 2025). "Subsequently, an experimental animal study demonstrated that myocardial ischemia-reperfusion injury was aggravated through the ROS/NLRP3 inflammasome-mediated pyroptosis pathway." (PMID 39493770, 2024). "To further elucidate the effects of tilianin on inhibiting NLRP3 inflammasome activation, we established an H9c2 cellular oxygen-glucose deprivation/reperfusion model to simulate the myocardial ischemia-reperfusion injury." (PMID 39508038, 2024). "In fact, NLRP3 inflammasome-mediated inflammation is initiated in the early stages of myocardial ischemia and can persist for days, exerting a profound influence on chronic outcomes like cardiac remodeling and congestive heart failure." (PMID 38279290, 2024). "In conclusion, this study demonstrated that the TLR4/NF-κB/NLRP3 pathway is involved in the anti-inflammatory and anti-myocardial ischemia/reperfusion injury (MIRI) properties of tilianin." (PMID 39508038, 2024). "Overall, tilianin suppresses NLRP3 inflammasome activation in myocardial ischemia/reperfusion injury by inhibiting the TLR4/NF-κB and NEK7/NLRP3 pathways." (PMID 39508038, 2024). "Using a cardiac ischemia-reperfusion animal model to mimic cardiac surgery, we assessed delirium-like behaviors, microglial activation, NLRP3 inflammasome activation, mitophagy, synaptic engulfment, and synaptic plasticity." (PMID 37968531, 2024). "A study found activation of NLRP3 inflammasomes in a mouse model of myocardial ischemia/reperfusion injury and high levels of NLRP3 further aggravated myocardial injury." (PMID 39022620, 2024). "One of the significant repercussions of myocardial ischemia and reperfusion injury post-MI is the pronounced inability to suppress the proinflammatory cell-death pathway governed by the NLRP3 inflammasome." (PMID 38279290, 2024).
myocardial ischemia (continued). "The researchers reported that UA aggravates ROS generation to promote the NLRP3 activation and pyroptosis in the myocardial ischemia–reperfusion (MI/R) model, while inflammasome inhibitors and ROS scavengers ameliorate MI/R damage." (PMID 37193772, 2023). "Recently, growing evidence suggests that NLRP3 inflammasome activation-mediated pyroptosis contributes to regional myocardial ischemia–reperfusion injury, which leads to myocardial dysfunction." (PMID 34973094, 2023). "Studies have shown that NLRP3 inflammasomes exert an injurious effect in promoting pyroptosis and inflammatory cascades during myocardial ischemia–reperfusion." (PMID 37853132, 2023). "DAPA attenuated myocardial ischemia/reperfusion injury by limiting NLRP3 inflammasome activation and modulating autophagy independently of its hypoglycemic effect." (PMID 37587757, 2023). "HMGB1 is up-regulated in a myocardial ischemia–reperfusion injury model, which increases the expression level of phosphorylated NF-κB p65, activates the NLRP3 inflammasome and induces the release of mature IL-1β." (PMID 35865525, 2022). "It exerted anti-inflammatory effects and attenuated myocardial ischemia-induced injury by inhibiting the TLR4/NF-κB/NLRP3 signaling pathway." (PMID 35664944, 2022). "By contrast, calpain silencing would attenuate mice myocardial ischemia/reperfusion injury via down regulating the NLRP3/Caspase 1 axis." (PMID 35155498, 2022). "As a targeted inhibitor of NLRP3, oridonin has also opened up new ways of thinking for the remedy of acute myocardial ischemia-reperfusion injury." (PMID 36421808, 2022). "NLRP3 overexpression is a major cause of coronary artery disease (CAD) and myocardial ischemia-reperfusion (I/R) damage." (PMID 35615687, 2022). "A recent study shows that the interaction between TXNIP and NLRP3 is the key point in the damage-induced myocardial ischemia." (PMID 33567593, 2021). "The role of artemisinin in myocardial ischemia/reperfusion (I/R) injury and the involvement of NLRP3 inflammasome were tried in an animal model." (PMID 34443594, 2021). "More specifically, inhibition of the NLRP3 inflammasome significantly reduced the infarct size and preserved cardiac function that accompany myocardial ischemia." (PMID 34472725, 2021). "In a study on cardiac ischemia-reperfusion, the authors showed that the NLRP3 inflammasome is increased in cardiac endothelial cells via TXNIP." (PMID 33567593, 2021). "The formation and activation of NLRP3 inflammasome promotes further myocardial injury after cardiac ischemia reperfusion.." (PMID 33823789, 2021). "On one hand, some studies have found that NLRP3 is upregulated in rat models of myocardial ischemia reperfusion, and the NLRP3 inflammasome level decreased by drugs can alleviate myocardial injury." (PMID 34422094, 2021). "In conclusion, the present study provides primary evidence that PBA improved myocardial ischemia reperfusion injury via suppression of NLRP3 inflammasome activation." (PMID 33391509, 2021). "Meanwhile, scutellarin also protected against myocardial ischemia–reperfusion injury by suppressing NLRP3 inflammasome activation." (PMID 33188176, 2020). "Prevention of NLRP3 activation in the priming phase during acute myocardial ischemia is sufficient to inhibit the inflammasome and protecting heart function." (PMID 31816891, 2019). "As in DCM, NLRP3 inflammasome also plays an important role in myocardial ischemia/reperfusion (I/R) injury after high-fat high-fructose (HFHF) diet, which is a common type of cardiometabolic disease." (PMID 28790925, 2017). "NLRP3 inflammasome activation plays an important role in myocardial ischemia/reperfusion (MI/R) injury." (PMID 29062465, 2017). "Although the nucleotide-binding oligomerization domain- (NOD-) like receptor pyrin domain containing 3 (NLRP3) inflammasome has been recently detected in the heart, its role in cardiac ischemia/reperfusion (IR) is still controversial." (PMID 28053692, 2016).